MYD88 (MYD88 innate immune signal transduction adaptor)
Description:
Adapter protein involved in the Toll-like receptor and IL-1 receptor signaling pathway in the innate immune response. Acts via IRAK1, IRAK2, IRF7 and TRAF6, leading to NF-kappa-B activation, cytokine secretion and the inflammatory response. Increases IL-8 transcription. Involved in IL-18-mediated signaling pathway. Activates IRF1 resulting in its rapid migration into the nucleus to mediate an efficient induction of IFN-beta, NOS2/INOS, and IL12A genes. Upon TLR8 activation by GU-rich single-stranded RNA (GU-rich RNA) derived from viruses such as SARS-CoV-2, SARS-CoV and HIV-1, induces IL1B release through NLRP3 inflammasome activation. MyD88-mediated signaling in intestinal epithelial cells is crucial for maintenance of gut homeostasis and controls the expression of the antimicrobial lectin REG3G in the small intestine (By similarity).
Synonyms: IMD68; MYD88D; WM1
Tractability: Antibody: its Gene Ontology location is reachable by antibodies, with high confidence. PROTAC: UniProt records ubiquitination sites on it; ubiquitination databases record sites on it; its protein half-life has been measured.
Safety:
Unwanted effects reported when the protein is acted on. In parentheses: how it was acted on, where the effect was seen, and who reports it.
cognitive dysfunction (source: ClinPGx)
Gene: Protein-coding gene on chromosome 3 (38,138,552 to 38,143,024, forward strand). Ensembl gene ENSG00000172936.
Subcellular location: Cytoplasm; Nucleus
Subcellular location (Human Protein Atlas): Cytosol; Mitochondria; Vesicles
Pathways (Reactome):
Immune System: DEx/H-box helicases activate type I IFN and inflammatory cytokines production; ER-Phagosome pathway; Interleukin-1 signaling; MyD88 cascade initiated on plasma membrane; MyD88 dependent cascade initiated on endosome; MyD88:MAL(TIRAP) cascade initiated on plasma membrane; RIP-mediated NFkB activation via ZBP1; TRAF6 mediated IRF7 activation in TLR7/8 or 9 signaling; TRAF6 mediated induction of NFkB and MAP kinases upon TLR7/8 or 9 activation
Disease: IRAK4 deficiency (TLR2/4); IRAK4 deficiency (TLR5); MyD88 deficiency (TLR2/4); MyD88 deficiency (TLR5)
Signal Transduction: PI5P, PP2A and IER3 Regulate PI3K/AKT Signaling; PIP3 activates AKT signaling; p75NTR recruits signalling complexes
Gene Ontology:
Molecular function: identical protein binding; molecular adaptor activity; protein binding; signaling adaptor activity; TIR domain binding; death receptor binding; Toll-like receptor binding; ATP-dependent histone chaperone activity; cytokine receptor binding; interleukin-1 receptor binding; signaling receptor binding; Toll binding
Biological process: 3'-UTR-mediated mRNA stabilization; apoptotic process; cellular response to mechanical stimulus; defense response to bacterium; defense response to virus; interleukin-1-mediated signaling pathway; interleukin-33-mediated signaling pathway; phagocytosis; positive regulation of canonical NF-kappaB signal transduction; positive regulation of cytokine production involved in inflammatory response; positive regulation of interleukin-1 beta production; positive regulation of interleukin-8 production; positive regulation of NLRP3 inflammasome complex assembly; positive regulation of type I interferon production; response to interleukin-1; toll-like receptor 4 signaling pathway; toll-like receptor 5 signaling pathway; toll-like receptor 8 signaling pathway; toll-like receptor 9 signaling pathway; toll-like receptor TLR6:TLR2 signaling pathway; type I interferon-mediated signaling pathway; canonical NF-kappaB signal transduction; cell surface receptor signaling pathway; cellular response to lipopolysaccharide; cellular response to oxidised low-density lipoprotein particle stimulus; and 26 more
Cellular component: cell surface; cytoplasm; cytosol; extrinsic component of cytoplasmic side of plasma membrane; extrinsic component of plasma membrane; nucleus; plasma membrane; endosome membrane; serine/threonine protein kinase complex; protein-containing complex
Genetic constraint (gnomAD): Loss-of-function variants: 15 observed, 32.03 expected, observed/expected ratio (o/e) 0.47, 90% interval 0.31 to 0.72. The upper end of that interval is the gene's LOEUF score, 0.72, which puts it in group 2 of 6, group 1 being the genes least tolerant of losing a copy. Missense variants: 308 observed, 403.55 expected, observed/expected ratio (o/e) 0.76, 90% interval 0.69 to 0.84. Synonymous variants: 157 observed, 166.45 expected, observed/expected ratio (o/e) 0.94, 90% interval 0.83 to 1.08.
Cancer hallmarks: proliferative signalling (promotes); escaping programmed cell death (promotes); invasion and metastasis (promotes); tumour promoting inflammation (promotes)
Homologues: Orthologues: chimpanzee MYD88 (99% identical), macaque MYD88 (99% identical), dog MYD88 (91% identical), pig MYD88 (88% identical), guinea pig MYD88 (87% identical), mouse Myd88 (82% identical), rat Myd88 (82% identical), tropical clawed frog myd88 (61% identical), zebrafish myd88 (60% identical), Drosophila melanogaster Myd88 (28% identical).
Diseases named in the same sentence as MYD88 in open-access papers:
MYD88 is named in the same sentence as 618 diseases in open-access papers, as found by Europe PMC text mining. Sharing a sentence is not in itself a finding about the gene and the disease. The quoted sentences say what the papers report.
colitis (199 papers, 2007 to 2025). Inflammation of the colon. "The potential of ACP as a treatment for liver inflammation linked to colitis is highlighted by its capacity to suppress the TLR4/MyD88/NF-κB pathway in the liver." (PMID 40725052, 2025). "Collectively, muscone has been shown to alleviate symptoms associated with DSS-induced colitis, potentially through the inhibition of the MyD88/p38 MAPK signalling pathway." (PMID 40452925, 2025). "The inhibitory effect of nutritional components in DM on the TLR4/MyD88/NF‐κB pathway likely underlies its ameliorative action against DSS‐induced colitis." (PMID 40994452, 2025). "L. plantarum strains (e.g., L15, ELF051) have been shown to suppress NF-κB activation through downregulation of the TLR4/MyD88 axis, reducing pro-inflammatory cytokine expression in murine models of colitis and antibiotic-associated diarrhoea." (PMID 41141596, 2025). "KEGG pathway analysis showed that immune-related pathways, including the IL-17, TNF, and NLR signaling pathways were the major pathways associated with MyD88 inhibition in DSS-induced colitis." (PMID 38946731, 2024). "In a mouse model of azoxymethane/DSS-induced colitis-associated cancer, administration of a MyD88 inhibitor significantly alleviated azoxymethane/DSS-inaduced colitis, resulting in reduced body weight loss and lower mortality rates." (PMID 38946731, 2024). "In our study, RNA transcriptome analysis showed that the NLR signaling pathway was the primary upregulated immunological pathway associated with MyD88 suppression in DSS-induced colitis." (PMID 38946731, 2024). "MyD88 plays dual functional roles in colorectal carcinogenesis and the role in promotion or reduction of tumor development and growth depends on the colitis-associated cancer animal models used." (PMID 38110638, 2023). "It is proven that blocking MyD88 signaling can prevent colitis-associated colorectal cancer (CAC) development in mice." (PMID 38110638, 2023). "We have shown in the past that deletion of immune-related genes, such as Ikk2 and Myd88 in Col6a1+ fibroblasts, results in reduced spontaneous and/or colitis-associated carcinogenesis." (PMID 38203319, 2023). "Expression of TNF receptor 1 Tnfr1, the proinflammatory cytokine Il1β and the adaptor protein Myd88 were also increased during experimental colitis in MCJ-deficient mice." (PMID 37805634, 2023). "Previous studies have proven that blocking MyD88 signaling with a novel MyD88 inhibitor (TJ-M2010-5, synthesized by Zhou’s group) completely prevented colitis-associated colorectal cancer (CAC) development in mice." (PMID 35089465, 2022). "Previous studies have shown that colitis in IL-10-/- mice is primarily caused by colonic macrophages induced by MyD88 signaling triggered by the intestinal microbiota." (PMID 36713373, 2022). "Numerous evidence disclosed that the activation of the TLR4/MYD88/NF-κB signaling pathway is associated with the pathogenesis of colitis." (PMID 34683415, 2021). "Consistently, Tlr4- and Myd88-KO mice are more susceptible to infection and colitis than WT mice due to increased bacterial translocation and decreased AMP expression." (PMID 33767714, 2021). "Mice deficient for either TLR2, 4, 5, and 9, the TLR-pathway mediator MyD88 or the NLRP6 inflammasome are highly susceptible to experimentally induced colitis." (PMID 33538854, 2021). "A study has confirmed that MAL serves as a bridge between TLR2/TLR4- and MyD88-mediated signaling to orchestrate downstream inflammatory responses and regulate intestinal homeostasis and colitis-associated colorectal cancer in mice." (PMID 32099532, 2020). "While the precise mechanism of action remains to be investigated, the susceptibility of MyD88-deficient mice to colitis has been linked to gut microbiota composition, which is altered in IBD." (PMID 31026259, 2019).
colitis (continued). "Rakoff-Nahoum and co-workers were the first to show that mice with global deficiency in MyD88 develop more severe colitis with colonic bleeding and increased mortality after chemical injury by oral application of DSS." (PMID 29570694, 2018). "The MyD88 inhibitor TJ-M2010-5 improved azoxymethane/DSS colitis and consequent colitis-associated colonic cancer." (PMID 29515999, 2018). "The TLR pathway, through signaling by the myeloid differentiation primary response gene 88 (MyD88)-dependent pathway, increases the risk of colitis (or other inflammatory bowel diseases; IBDs)-associated CRC due to commensal gut microbiota." (PMID 29883450, 2018). "Deletion of TLR4, TLR2, TLR5 and TLR9 as well as simultaneous deletion of TLR3 and TLR7 led to disturbed epithelial homeostasis and enhanced susceptibility to acute DSS-induced colitis, however with less severe pathology than in MyD88-deficient mice." (PMID 29570694, 2018). "To assess the effects of IL-33 on enterocyte differentiation early in colitis and the contribution of MyD88 to these effects, we i.p. injected wild-type or MyD88-deficient mice with mrIL-33 after low-dose TNBS administration." (PMID 28404987, 2017). "Treg-specific deletion of MyD88 has been recently shown to culminate in deficiency of Treg cells, increase in Th17 cells, and exacerbated experimental colitis." (PMID 26925061, 2016). "We found that co-infection with the helminth parasite significantly worsened Citrobacter-induced colitis in the MyD88-deficient mice, in association with increased mortality and compromised innate immune responses." (PMID 25010669, 2014). "The myeloid differentiation primary response gene 88-(MyD88) signaling pathway has been implicated in perpetuating the inflammatory response in experimental peritonitis and colitis." (PMID 22619481, 2012). "For example, PAMP-sensing by intestinal epithelial cells has been reported to induce the expression of bactericidal and barrier-enhancing mediators, and deficiency in TLR2, TLR4 or MyD88 was shown to result in increased mortality following DSS-induced colitis." (PMID 20161736, 2010). "S. Typhimurium can induce colitis in streptomycin-treated Myd88-deficient mice suggesting that signaling through most TLRs is not required to induce inflammation in this infection model." (PMID 19662166, 2009). "The potential mechanism underlying the mitigation of colitis may involve the inhibition of the MyD88/p38 MAPK signalling pathway." (PMID 40452925, 2025). "Similarly, recent findings have shown that the TLR4/MyD88 signaling pathway is strongly linked with the inflammatory response in the colitis mouse model and fulfills a crucial role in the pathogenesis of colitis." (PMID 38611304, 2024). "Additionally, according to Araki and colleagues, MyD88-deficient animals given DSS developed severe colitis unexpectedly." (PMID 39323474, 2024). "However, inhibition of MyD88 did not significantly ameliorate the disease severity of acute DSS-induced colitis, which was in concordance with data from MyD88-deficient mice." (PMID 38946731, 2024). "Thus, it is systemically blocking MyD88 signaling pathway instead of lymphocyte-specific MyD88 deficiency that is beneficial to maintain colonic microbiota homeostasis and to prevent colitis and CAC development." (PMID 38110638, 2023). "Similarly, depletion of MyD88 prevents spontaneous colitis caused by Il10 deficiency and chronic inflammation in response to commensal microbes." (PMID 37215126, 2023). "In addition, the MyD88 deficient mice displayed exacerbated colitis severity with gut dysbiosis highlighted by an overabundance of SFB and increased bacterial load, indicating MyD88 signaling is needed in IgA responses to IBD and gut dysbiosis." (PMID 34683438, 2021). "Moreover, studies have demonstrated that high expression of TLR4/MyD88 is associated with liver metastases and is an independent predictor for poor prognosis, both in colitis-associated and in sporadic CRC cases." (PMID 29883450, 2018).
colitis (continued). "Reflecting the importance of these homeostatic functions, selective depletion of mφ by targeting the CSF1R leads to enhanced susceptibility to dextran sodium sulfate (DSS)-induced colitis 42 and epithelial repair in this model requires MyD88 signaling in myeloid cells." (PMID 24942685, 2014). "Consistently, recent reports further emphasize that IL1R, IL18R or IL18 deficiency renders mice highly susceptible to DSS-induced colitis indicating that signaling through MyD88 is required to preserve the intestinal barrier and to promote repair following injury." (PMID 24886810, 2014). "Mice ablated of TLR2, TLR4, TLR9, or their common adaptor molecule MyD88, were more acutely susceptible to colitis induced by the chemical colitogen dextran sodium sulfate (DSS), due in part to impaired protective responses and reduced prostaglandin production." (PMID 20885960, 2010). "But our knowledge of how commensal-dependent TLRs, upstream of MyD88, may differentially regulate the phenotype of colitis in the IL-10-deficient host remains so far limited." (PMID 20803699, 2010). "Studies have reported that berberine can inhibit the TLR4/MyD88/NF-κB signaling pathway, thereby ameliorating colonic inflammatory responses and intestinal epithelial barrier dysfunction in colitis mice." (PMID 39810933, 2025). "Baicalein has been shown to attenuate TNBS-induced colitis by inhibiting the TLR4/MyD88 signaling cascade and inactivating the NLRP3 inflammasome." (PMID 40130239, 2025). "Overall, these data indicate that SPARC influences intestinal epithelial barrier and colitis progression by modulating MYD88/NF‐κB signaling." (PMID 39888301, 2025). "Although these microbial changes do not induce inflammation under normal conditions, they exacerbate intestinal inflammation in the context of DSS induced colitis through the activation of innate immune cells and the IL-18/MyD88-dependent signaling pathways." (PMID 41133791, 2025). "The inflammatory process in colitis involves a cascade of interactions among several crucial proteins, with MyD88 serving as a central player." (PMID 40452925, 2025). "The activation of the TLR4/MyD88/NF-κB signaling cascade—triggered by conditions such as colitis or LPS binding to TLR4—promotes the release of pro-inflammatory cytokines, thereby amplifying the inflammatory response." (PMID 41300540, 2025). "Studies have shown that trinitrobenzene sulfonic acid (TNBS)-induced colitis is ameliorated by inhibiting MyD88 expression, which subsequently downregulates downstream caspase-3 expression." (PMID 40452925, 2025). "Collectively, our findings suggest that inulin intake exacerbates DSS induced colitis through microbiota-mediated inflammation and MyD88/IL-18 signaling, with the effects persist in the offspring." (PMID 41133791, 2025). "Numerous studies have reported that colitis upregulates MyD88 levels, thereby triggering signalling cascades involved in apoptosis and the mitogen-activated protein kinase (MAPK) and NF-κB pathways." (PMID 40452925, 2025). "Casein, α‐lactalbumin, and L‐isoleucine have been demonstrated to alleviate DSS‐induced colitis by suppressing the TLR4/MyD88/NF‐κB signaling pathway." (PMID 40994452, 2025). "In mouse models with dextran sulphate sodium (DSS) induced colitis, d‐Ala supplementation suppressed the growth of harmful bacteria (E. coli and K. pneumoniae) alleviating colitis primarily by modulating Toll‐like receptors–MyD88 signaling." (PMID 40146632, 2025). "Consistent with this, after infection with type B2 Escherichia coli, mice exhibit TLR4/MyD88/NF-κB activation and typical clinical symptoms and pathological changes of colitis." (PMID 40076603, 2025). "In DSS-induced colitis, the mRNA expression of NF-κB, MyD88, and TRAF6 was elevated (p < 0.05), while the expression of p-p65 was significantly up-regulated in the colons of mice in the DSS group (p < 0.01)." (PMID 40130239, 2025).